TNF (tumor necrosis factor)
Diseases named in the same sentence as TNF in open-access papers (continued):
Sharing a sentence is not in itself a finding about the gene and the disease.
tumor (continued). "We have previously shown that the MAPK activated protein kinase 2 (MK2) pathway is responsible for the majority of IL-1β, IL-6, and TNF-α production in both a colitis-associated cancer and a tumor transfer model of CRC." (PMID 30298062, 2018). "The level of ALCAM transcripts was positively associated with the expression of tumor necrosis factor α (TNFα), nuclear factor-kappa B (NF-κB) p50 subunit, and interleukin (IL)-4 in tumor tissues (p < 0.001, p < 0.001 and p = 0.012, respectively)." (PMID 29315254, 2018). "TNF-α is a fundamental tumor promoter in inflammation-associated carcinogenesis; the PTX-induced reduction in the expression levels of TNF-α in the colonic mucosa observed in this study is therefore of importance." (PMID 28212276, 2017). "The complete tumor regression in most of the TNF-deficient mice precluded analysis of TILs at later time points under our experimental conditions." (PMID 29273790, 2017). "The levels of elevated plasma TNF-α are commonly associated with poor prognosis, such as tumor recurrence and positive lymph-node stage." (PMID 28575042, 2017). "This is analogous to vertebrate tumor-associated macrophages promoting tumor function and pro-inflammatory cytokine production through TNF-α signaling." (PMID 28171746, 2017). "SSeCKS is known to be normally upregulated by inflammatory mediators such as LPS or TNFα, and thus, SSeCKS downregulation in tumor-associated stroma must result from tumor-derived cross-talk factors." (PMID 29050279, 2017). "Herein, we noticed that anti-PD-1 therapeutic effect was dramatically enhanced in TNFR1-deficient mice, indicating that TNFR1-dependent TNF signalling in the tumor microenvironment also critically contributes to anti-PD-1 therapy resistance." (PMID 29273790, 2017). "Some proinflammatory cytokines (such as TNF-α, IL-1, and IL-6) that are encoded by target genes of the NF-κB pathway contribute to inflammation-related tissue damage and are associated with tumor development and progression." (PMID 28852270, 2017). "In another study, a tumor-targeted replication-competent virus (oncolytic virus) carrying the genes encoding for IL-2 and TNF-α, was used for IL-2 delivery to the tumor site." (PMID 28927416, 2017). "TNF has been covalently conjugated to gold nanoparticles, with the aim of the interaction between TNF and its receptor TNF-R1 causing active targeting of the tumour cells." (PMID 28217176, 2017). "Another important inflammatory cell type, tumor-associated macrophages, also promote tumor progression and metastasis by producing cytokines such as TNF-α, IL-1, IL-6, and transforming growth factor beta (TGF-β)." (PMID 28737711, 2017). "Sustained production of pro-inflammatory cytokines, such as TNF-α, IL-6 and IL-1β, results in chronic inflammation, which, in turn, increases cancer risk, tumor development and progression." (PMID 29044191, 2017). "At any rate, it is possible that autocrine signaling by mTNF-αmay be one of many confounding factors, given studies showing that membrane-bound and soluble forms of TNF-α, expressed by tumor cells, have opposing effects on tumor-associated myeloid cells." (PMID 28915246, 2017). "SDF-1α and TGF-β1 are involved in promoting tumor growth, whereas proinflammatory cytokines, such as Il-1β and TNF-α are mainly produced by classically activated (M1 polarized) tumor-associated microglia/macrophages." (PMID 28415741, 2017). "It activates pro-inflammatory genes (COX-2, iNOS, TNF-α, IL-1, and IL-6) in tumor and tumor-associated cells and surrounding tissue, as well as antiapoptotic (Bcl-2, Bcl-X) and proangiogenic molecules (vascular endothelial growth factor)." (PMID 28487844, 2017). "TNF-α gene promoter-308 A/G single nucleotide polymorphisms are recently found to be significantly associated with the tumor-invasive stage of BCa." (PMID 29190997, 2017). "This was associated with reduced tumor cell proliferation and a significant reduction in IL-6, pSTAT3 and TNFα levels." (PMID 28416734, 2017).
tumor (continued). "A growing number of studies have reported the key role of TLR4/NF-κB/TNF-α signaling to promote tumor growth in experimental models of colitis associated cancer, whereas data from human CAC are rare." (PMID 28408791, 2017). "NGF caused a considerable increase in the level of TNF-α and IL-1β in the serum of the tumor-bearing mice." (PMID 28878143, 2017). "In recent studies, the association between tumor progression, metastasis and inflammatory mediators TNF-α, IL-6, vascular endothelial growth factor (VEGF) and C-C motif chemokine receptor 7 (CCR7) have also been investigated." (PMID 29299026, 2017). "The abscopal effects have been attributed to the induced inflammatory cytokines such as IL-1β, IL-6, and TNF-α released from the primary tumor site or non-tumor cells such as endothelial cells and cancer associated fibroblasts." (PMID 28977985, 2017). "A growing body of evidence showed that inflammatory cells usually produce large amounts of pro-tumorigenic cytokines, such as TNF, Interleukin-6 and Interleukin-23, which cause cell proliferation and tumor progression in colorectal cells." (PMID 29657291, 2017). "The pro-inflammatory cytokines; IL-1β, IL-6, TNF-α and GM-CSF have been implicated in cell biology changes required for tumour progression." (PMID 28427184, 2017). "One study showed that the synergistic response of TGF-β and TNF-α is an important in vivo mechanism blocking IFN-I production by tumor-associated pDCs through the inhibition of IRF7 signaling and nuclear translocation in gynecological malignancy." (PMID 29085361, 2017). "CSF-1 influences also the maturation of tumor-associated macrophages; in CSF-1 deficient animals macrophages remained more immature with lower expression of IL-1β, TNF-α." (PMID 28197019, 2017). "In polarity gene mutation-mediated tumors, macrophages inhibit tumor growth via the production of the Drosophila tumor necrosis factor (TNF) ortholog, Eiger." (PMID 28171746, 2017). "Macrophages contribute to cancer-related inflammation and sequential production of cytokines such as IL-6 and TNF-α which cause various biological processes that promote tumor initiation, growth and metastasis." (PMID 28969049, 2017). "The combined therapy of irradiation and anti-PD-L1 treatment resulted in activation of cytotoxic T cells and synergistic elimination of MDSCs by T cell-generated TNF, which is associated with delayed tumor growth." (PMID 28603525, 2017). "Although IFN-γ primarily had anti-vascular pro-apoptotic activity, low-dose TNF-α stabilized the tumour-associated vascular network and enhanced CD8 effector T-cell activity." (PMID 28300057, 2017). "Physicochemical characteristic of CRC patients classified by tumor site and TNF-α -308 polymorphism." (PMID 28575042, 2017). "Constitutive NF-κB activation causes Raji cells to be resistant to TNF-α-mediated cytotoxicity and sustains tumor cell survival." (PMID 29234328, 2017). "Induction of mitochondrial apoptosis pathway involves Caspase‐9 activation, whereas extrinsic apoptosis pathway is triggered by tumour necrosis factors (e.g. TNF‐a or FasL) binding to death domain receptors, in turn causing subsequent activation of Caspase‐8." (PMID 28468958, 2017). "At day 10, tumor weights were significantly reduced in TNF-deficient mice as compared to WT mice, and this phenomenon was further amplified upon anti-PD-1 injection." (PMID 29273790, 2017). "The existence of TNF-α secreted in autocrine or paracrine manner by component of tumor microenvironment highlights the significance of TNF-α in inflammation-associated tumor metastasis." (PMID 27556690, 2016). "TNF-α and its soluble receptor sTNFr1 have been implicated in cancer physiology as both promotors and inhibits of tumour progression." (PMID 27170831, 2016). "Intriguingly, TNFα and TNFR1showed divergent role in inflammation-associated hepatocarcinogenesis, and for the first time, the anti-tumor function of IL6 in HCC was revealed in present study." (PMID 27556180, 2016).
tumor (continued). "We also evaluated the association of TNF-α-308G/A SNP with the subsets of various characteristics of the case group subjects under study i.e. age, gender, dwelling, smoking status, tumor location, tumor grade and lymph node status." (PMID 27331018, 2016). "TNF-α is known to play a particular role in enhancing tumor cell migration and invasion, but the underlying mechanisms are still elusive." (PMID 27042827, 2016). "Taken together, these data suggest that vancomycin-sensitive bacteria caused recruitment of neutrophils, which promoted TNFα and iNOS expression, followed by epithelial tissue damage, DNA damage, and tumor growth." (PMID 27050089, 2016). "TNF-α is a key cytokine in the inflammatory response caused by tissue destruction, bacterial infection and tumor cells, and it can induce the occurrence of and worsen inflammation." (PMID 27445818, 2016). "Our results would thus be consistent with an antigen-driven activation of circulating macrophages that are induced to secrete inflammatory cytokines, especially IL-6 and TNFα, potentially associated with an anti-tumor effect." (PMID 27662661, 2016). "Actors of this inflammatory process, such as tumor-associated macrophages (TAMs) or MDSCs and their secreted cytokines (IL-6, IL-1β, TNF) are now considered as key in promoting tumor progression." (PMID 27713124, 2016). "TNF signaling has been implicated as having either tumor-suppressive or tumor-promoting activity depending on biological context." (PMID 27454609, 2016). "TNF-α, released in the tumour microenvironment, is linked with tumour progression inducing degranulation of the neutrophils, releasing VEGF and favouring angiogenesis with the production of CXCL8 and CXCL1." (PMID 26913068, 2016). "Production of inflammatory cytokines such as TNFα by tumor associated macrophages can enhance the development and progression of various malignancies." (PMID 27129149, 2016). "We have shown previously that the expression of TNFα in the tumour islets is also associated with improved survival." (PMID 27922077, 2016). "In the tumor microenvironment, TNFα is produced by tumor cells as well as tumor-associated cells and plays a central role in promoting tumor invasion and metastasis." (PMID 27776550, 2016). "Of potential importance, both protease phenotypes are present within the tumour islets of patients with ES, they express TNFα, and the presence of both is associated with increased survival following surgical resection." (PMID 27922077, 2016). "The TCP-1/TNFα and TCP-1/IFNγ combined treatment group inhibited tumor growth by different mechanisms from targeted TNFα or IFNγ alone which is highly associated with antitumor immunity." (PMID 27342639, 2016). "We have shown previously that increased expression of TNFα in the tumour islets of patients with NSCLC is independently associated with improved survival." (PMID 27922077, 2016). "Recent researches reported that tumor associated genes including Bcl-2, c-fos, and tumor necrosis factor-α (TNF-α) were regulated by CREB1." (PMID 27801665, 2016). "BRAF inhibition has been shown to increase immune reaction in the tumor microenvironment and is associated with high serum tumor necrosis factor level." (PMID 26152183, 2015). "M1 macrophages with TNF-α/IL-1β production and an active NF-κB pathway are central to tumor causal inflammation and play an important role in tumorigenesis." (PMID 26684869, 2015). "Tumour necrosis factor (TNF-α) is an inflammatory mediator present in the tumour microenvironment that has been implicated in carcinogenesis, especially in the early stages, including angiogenesis and invasion, versus the progression of carcinogenesis." (PMID 26508818, 2015).
tumor (continued). "It has been shown that TNFα-deficient mice are largely resistant to tumour formation in the DMBA/TPA model." (PMID 26079427, 2015). "A likely scenario was that TNF-α affected the anti-tumor immune response indirectly via inducing killing of tumor cells and promoting destruction of tumor-associated vasculature." (PMID 26107883, 2015). "In recent years, there have been many documents reported the multiple side effects accompanied with anti-TNF-α therapies, such as the increased risk of severe viral and bacterium infection, anaphylaxis, and tumor." (PMID 25178696, 2015). "Several proinflammatory cytokines and chemokines such as IL-1, IL-6, TNF, and IL-8 are often upregulated in response to cancer and are associated with tumor development and progression in mice." (PMID 26425120, 2015). "This communication presents evidence that novel intravenously administered DAB-LF and DAB-LFC dendriplexes encoding TNFα led to tumor regression and even complete tumor suppression in some cases." (PMID 25933695, 2015). "The fever and TNFα work in synergy to eliminate the most dangerous cells: those with high mutation rates and low perfusion; these tumor cells are the most resistant to systemic cancer therapies." (PMID 25592450, 2015). "In contrast to tumor-cytotoxic effects caused by acute local TNF-α administration, chronic and persistent presence of TNF-α in tumors has strong pro-tumoral effects in many cancers." (PMID 25928089, 2015). "TNF-α is a multifunctional cytokine that can cause direct tumor necrosis by inflicting tumor-associated capillary injury, but also generates an adaptive immune response." (PMID 26697006, 2015). "A recent study provides evidence that loss of SOCS1 expression inside tumor cells via promoter hypermethylation is strongly associated with overproduction of inflammatory cytokines like TNF-α and IL-6." (PMID 25814785, 2015). "A prominent example of cytokine subjected to post-transcriptional control is tumor necrosis factor alpha (TNF-alpha or TNF), one of the main mediators of chronic inflammation associated with malignant cell transformation, growth and tumor progression." (PMID 26553968, 2015). "Tumour presence has been associated with elevated serum IL-6 and TNF-α in mice bearing the Lewis lung carcinoma or B16 melanoma cells compared to controls." (PMID 26508820, 2015). "First, we demonstrated that TNF induces migration of tumor associated macrophage-like THP-1 and CRPC C4-2 cells in a cell culture model of the tumor microenvironment." (PMID 26327448, 2015). "In this case, catabolic factors, such as IL-6 and TNF-α, are increased, contributing to the loss of muscle mass, and it has been suggested that the tumour has a great influence on the increase in the circulation of these factors." (PMID 26508818, 2015). "TNF-α is known to have a double-edged role in tumours and is often associated with inducing cancer, angiogenesis, proliferation and metastasis." (PMID 25902944, 2015). "Multi-regression analysis showed that TNF-α-308A was also a risk factor for distant tumour metastasis after adjustment for tumour size and lymph node metastasis status (OR = 6.26, 95% CI: 1.88–20.87, P = 0.003)." (PMID 26165253, 2015). "From the hypoxically suppressed proinflammatory genes identified by RNA sequencing, four secreted inflammatory factors (CCL20, CXCL5, CSF2 and TNFα) associated with tumor inflammation were chosen for further validation." (PMID 25978030, 2015). "TNF-α was identified by studying its antiangiogenic activity; when injected into tumors, it causes tumor vessel regression, resulting in tumor necrosis." (PMID 26137497, 2015). "Previous studies showed that TNFα can act as an autocrine tumor growth factor and that its presence is associated with poor prognosis." (PMID 26447542, 2015).
tumor (continued). "These cancer and stromal cells secrete vascular endothelial growth factor (VEGF), fibroblast growth factor 2 (FGF2), tumor necrosis factor-α (TNF-α), and IL-6 into the surrounding area and these factors contribute to tumor-associated angiogenesis." (PMID 25502753, 2014). "These SOCS3-deficient macrophages produce less IL-6 and TNF-α upon stimulation with tumor lysates due to aberrant STAT3 activity, again showing a positive link of SOCS and macrophage polarization." (PMID 25120543, 2014). "The introduction of biologic therapies to the management of RA has raised concerns about the risk of cancer, particularly with respect to anti-TNF therapies, due to the role of TNF in tumor progression and surveillance." (PMID 25267341, 2014). "The role of TNF and IL-6 as master regulators of tumour-associated inflammation and tumourigenesis makes them attractive targets for adjuvant treatment in cancer." (PMID 24667059, 2014). "Tumor-associated DC can directly drive tumor angiogenesis through the release of pro-angiogenic cytokines such as TNFα, CXCL8, and osteopontin." (PMID 24782982, 2014). "ADAM17 is involved in the cleavage of numerous surface molecules, most of which are considered to be relevant in tumour-associated processes such as cell growth, migration and invasion (TNF-α, CD44, L1-CAM, L-selectin, ICAM1, CX3CL1, etc.)." (PMID 25246708, 2014). "Tetramer and intracellular staining for IFN-γ and TNF-α demonstrated a loss of CTL activity in B16-OVA-shUSP18 tumor-bearing mice." (PMID 24884733, 2014). "In human colon cancer cells, TIMP-1 conferred resistance against cytotoxicity caused by TNF-α and IL-2, and contributed to clonogenicity and tumor growth during early tumor formation." (PMID 24518611, 2014). "In a chronic inflammatory process, cytokines such as TNF-α and IL-6 induce the generation of free radicals that can damage DNA, potentially causing mutations that lead to tumor initiation." (PMID 24901008, 2014). "Of these cytokines, proinflammatory cytokines, including TNF-a and IL-6, have been demonstrated to activate the NFkB pathway which is then associated with tumor progression." (PMID 24732966, 2014). "The mast cells will also release TNFα and Serotonin, causing upregulation of chemokines, selectins, and adhesion molecules and subsequent hapten-specific T-cell to trafficking to the tumor." (PMID 24949488, 2014). "The present study investigated the antitumor efficacy of recombinant mutated human TNF-α specifically targeted to the tumor vasculature (RGD-rmhTNF-α) combined with the chemotherapeutic agent doxorubicin in 2 murine allografted tumor models." (PMID 24466321, 2014). "This hapten-tumor IgM will also lead to the activation of mast cells which will release TNFα and CXCL2, causing cause FasL+, perforin+ neutrophil cell infiltration." (PMID 24949488, 2014). "TNF-α has been implicated in inflammation-associated cancer and is produced by tumor cells and/or infiltrating leukocytes." (PMID 24520307, 2014). "Tumour necrosis factor alpha (TNFα) is a monocyte derived cytotoxin implicated in tumour regression, septic shock and cachexia." (PMID 25391018, 2014). "It is thought that IL-10 deficiency leads to elevated levels of TNF-α, IL-6, and IL-17, which in turn allow persistence of chronic inflammation thus promoting tumor growth." (PMID 24639678, 2014). "Tumor-associated inflammatory cytokines, such as IL-6 and TNF-α, are likely to regulate cancer cells in the tumor microenvironment." (PMID 24396476, 2014). "SYD reduced the expression levels of serum interleukin 1β, interleukin-6, tumor necrosis factor α, tumor-associated macrophages, and p65." (PMID 24766737, 2014). "In 1968, TNF-α was identified as a soluble cytokine able to exert significant cytotoxicity on many tumor cell lines and to cause tumor necrosis in certain animal model systems." (PMID 23641196, 2013).